MTOR (mechanistic target of rapamycin kinase)
Diseases named in the same sentence as MTOR in open-access papers (continued):
Sharing a sentence is not in itself a finding about the gene and the disease.
vascular malformation (continued). "Research has consistently shown that overactivation of PI3K/AKT/mTOR pathway is associated with PIK3CA-related overgrowth spectrum (PROS) and slow-flow vascular malformations." (PMID 41430313, 2025). "Inhibitors of this pathway - including sirolimus (rapamycin), everolimus, and other allosteric mTOR inhibitors - have been used with some efficacy in managing vascular malformations and overgrowth syndromes." (PMID 40861611, 2025). "In recent years, it has become evident that different types of vascular malformations are linked to inherited and somatic mutations in the PI3K/AKT/mTOR and RAS/RAF/MEK pathways, both of which play a crucial role in cancer biology." (PMID 39407873, 2024). "Due to the availability and success of the mTOR inhibitor rapamycin in the treatment of LM and other vascular malformations, there has been a strong focus on the role of AKT/mTOR signaling in LM pathogenesis." (PMID 38488007, 2024). "The majority of mutations identified in vascular malformations occur within two key intracellular signaling pathways: the RAS-MAPK and PI3K/AKT/mTOR pathways." (PMID 38790562, 2024). "The higher expression of mTOR substrates in vascular malformations compared to healthy tissue confirms their involvement in abnormal vascular development." (PMID 38201347, 2023). "The efficacy of mTOR inhibitors indirectly suggests the deregulation of the mTOR pathway in vascular malformations and increased expression of certain key proteins involved in this metabolic pathway’s function." (PMID 38201347, 2023). "In this study, we aimed to investigate the activation of the mTOR pathway in a subset of vascular malformations." (PMID 38201347, 2023). "In conclusion, our study contributes to the understanding of the mTOR signaling pathway in vascular malformations and highlights its potential as a therapeutic target contributing to personalized medicine." (PMID 38201347, 2023). "Our study contributes to the understanding of the mTOR signaling pathway in vascular malformations and highlights its potential as a therapeutic target, contributing to personalized medicine." (PMID 38201347, 2023). "In conclusion, our study investigated the activation levels of mTOR pathway substrates in vascular malformations and explored their relationship with age." (PMID 38201347, 2023). "The results also suggest the potential utility of mTOR inhibitors, such as sirolimus, as an effective therapeutic option for vascular malformations." (PMID 38201347, 2023). "Given that pS6, a downstream effector of AKT/mTOR, is selectively activated in the presence of growth factors in mutant cells, it suggests that the AKT/mTOR axis orchestrates the onset of Pik3caH1047R‐vascular malformations." (PMID 35695059, 2022). "In the three published prospective clinical trials using Rapamycin, an mTOR inhibitor, on patients affected by various vascular malformations, response rates were high." (PMID 34112235, 2021). "Ongoing clinical trials assessing the efficacy of Sirolimus (mTOR inhibitor Rapamycin) for the treatment of PIK3CA-driven vascular malformations have shown promising results." (PMID 32513927, 2020). "Rapamycin and its analogues (sirolimus, everolimus) that target the PI3K downstream effector mTOR can stop the progression of vascular malformations in mice and human, and improve the patients’ quality of life." (PMID 32513927, 2020). "Sirolimus has been shown to improve various vascular malformations by suppressing activation of mTOR, S6K1 and 4EBP1." (PMID 32711543, 2020). "Rapamycin (also known as sirolimus) is an allosteric inhibitor of the PI3K downstream target mTOR that has been used in the treatment of patients with vascular malformations including both VM and LM3." (PMID 32513927, 2020). "This implies that fast and slow flow vascular lesions might share common molecular features and further proved the importance of excessive PI3K/AKT/mTOR activation in the etiology of vascular malformations." (PMID 41430313, 2025).
vascular malformation (continued). "Overactivation of PI3K/AKT/mTOR signaling pathway is central to the etiology of many vascular malformations, as this pathway represents a major hub that determines EC fate including EC growth, migration, actin cytoskeleton remodeling, metabolism, and vesicular trafficking." (PMID 41430313, 2025). "•Take Home Message: Direct stick embolization with this mTOR inhibitor may be safe and effective for the management of low-flow vascular malformations." (PMID 39515753, 2025). "Vascular malformations may benefit from targeting the dysregulated PI3K/AKT/mTOR pathway through PTEN restoration or mimetic compounds, potentially helping to modulate aberrant cellular growth and improve patient outcomes." (PMID 41430313, 2025). "Additionally, sirolimus, an mTOR inhibitor, has shown promise in reducing vascular malformations and improving symptoms." (PMID 39816300, 2024). "Sporadic vascular malformations (VMs) are a large group of disorders of the blood and lymphatic vessels caused by somatic mutations in several genes—mainly regulating the RAS/MAPK/ERK and PI3K/AKT/mTOR pathways." (PMID 35740480, 2022). "With the identification of the PI3K/AKT/mTOR pathway as an important driver of somatic overgrowth syndromes and the identification of somatic PI3K mutations within certain vascular malformations, PI3K inhibition has become the next major therapeutic target for vascular anomalies." (PMID 33194911, 2020). "Similarly, somatic/mosaic PIK3CA mutations are found in the majority of LM and complex malformations (KTS), underscoring mTOR activation as an interesting target for medical treatment of slow-flow vascular malformations." (PMID 30373605, 2018). "In addition to sclerotherapy and surgical excision, protein inhibitors involved in the signaling pathways PI3K/AKT/mTOR or RAS/BRAF/MAPK/ERK appear as targeted therapeutic options for different types of vascular malformations, so far, the clinical results being promising." (PMID 36293054, 2022). "As sirolimus targets cellular proliferation, survival and stemness via mTOR inhibition, its observed effect on some vascular tumors and vascular malformations, including overgrowth syndromes, may be attributed to its action on these primitive populations within these VAs." (PMID 33634164, 2020). "Mammalian target of rapamycin (mTOR) inhibitors, immunosuppressants used in transplant medicine, have been repurposed to target patients with PIK3CA-related vascular malformations and segmental overgrowth." (PMID 34916230, 2023). "In addition, somatic activating mutations of the PI3K/AKT/mTOR pathway may result in PIK3CA-related overgrowth spectrum diseases, including CLOVES (Congenital Lipomatous Overgrowth, Vascular malformation, Epidermal nevi, Skeletal abnormalities/Scoliosis) syndrome." (PMID 32660056, 2020). "Alternatively, sensitivity to mTOR inhibition could be due to the endothelial origin of EHE, as other vascular sarcomas and vascular malformations have elevated mTOR signaling and show sensitivity to Sirolimus." (PMID 40940986, 2025). "The use of Mammalian Target of Rapamycin inhibitors (mTOR inhibitors), such as sirolimus, shows promise in treating complex vascular malformations that are not amenable to surgical excision." (PMID 40310161, 2025). "Thus, despite the heterogeneity of genetic alterations across vascular malformations, PI3K/AKT/mTOR pathway consistently emerges as the central hub, governing EC growth, migration, cytoskeletal remodeling, and metabolism." (PMID 41430313, 2025). "Sirolimus, an mTOR inhibitor, targets this pathway and early research has demonstrated its effectiveness in the treatment for some vascular malformations, implying that the endothelium in AVM is not “quiescent,” as previously assumed." (PMID 34409065, 2021).
vascular malformation (continued). "The mTOR inhibitor sirolimus may also be worth studying in view of the established interaction and coregulation of PIK3CA/AKT/mTOR with the MAPK/MEK/Ras pathway, as well as its successful usage in treating complex vascular malformations." (PMID 37106420, 2023). "Recent preclinical and clinical data demonstrated that sirolimus could offset the progression of vascular malformations and significantly improve quality of life of patients through inhibition of the Phosphatidylinositol-3-kinase (PI3K)/AKT/mammalian Target of Rapamycin (mTOR) pathway." (PMID 30373605, 2018).
chordoma (42 papers, 2009 to 2025). Chordomas are rare malignant tumors arising from embryonic remnants of the notochord in axial skeleton. "The exploration of CTLA-4 and mTOR inhibitors also underlines the diverse strategies being pursued to address the complexity of chordoma pathogenesis." (PMID 38731241, 2024). "Nevertheless, mutations in PI3K/AKT/mTOR genes have been reported in chordoma tumors with potential therapeutic relevance." (PMID 34070849, 2021). "The genes TSC1 and TSC2, being of the mTOR pathway, have raised the possibility that this pathway is implicated in intracellular signalling for oncogenesis in chordomas." (PMID 26391590, 2015). "One of the reasons for embarking on the analysis of the mTOR pathway in chordomas was the reported loss of heterozygosity in chordomas in two individuals with tuberous sclerosis complex syndrome." (PMID 19401700, 2009). "However, investigation into mTOR activity in chordomas is required before offering such treatments as evidence also exists that the locus harbouring mTOR in chordomas is a region where there is frequent genomic loss (frequency of 0.57)." (PMID 19401700, 2009). "However, the availability of PTEN-deleted cell lines represents a useful tool to further investigate the functional role of PTEN deficiency and Akt/mTORC1 hyperactivation associated with chordomas and prove if mTOR inhibition is effective in suppressing tumour growth." (PMID 36983607, 2023). "Molecular therapy targets being investigated include several receptor tyrosine kinases (e.g., PDGFR, EGFR), downstream cascades (e.g., PI3K/Akt/mTOR), brachyury (a transcription factor unique to chordoma), and the FGF/MEK/ERK pathway." (PMID 39193055, 2024). "Loss of PTEN and CDKN2A (encoding p16) is one of the most common molecular changes seen in chordomas; poor prognoses are linked to particular inhibitors of the PI3K/AKT/mTOR pathway and CDK4/6." (PMID 39233954, 2024). "We exploited the oncogenic driver addiction in these chordomas by simultaneously inhibiting the PI3k/AKT/mTOR and CDK4/6 pathways." (PMID 37046638, 2023). "Several studies have shown that the mTOR pathway is hyperactivated in chordomas and have suggested it as a possible therapeutic target." (PMID 36983607, 2023). "mTOR inhibitors, including rapamycin, have been approved for a wide range of tumours and they have been also proposed for chordoma treatment." (PMID 36983607, 2023). "The therapeutical experience with inhibitors of the PI3K/AKT/mTOR pathway in chordomas is restricted to single case reports and clinical trials with small cohorts." (PMID 37046638, 2023). "One such pathway is that of mTOR, which is frequently hyperactivated in chordomas and has been suggested as a possible therapeutic target." (PMID 38022609, 2023). "Further imaging revealed growth of these lesions over the next 6 months, and he was initiated on imatinib and sirolimus, based on his underlying diagnosis of TS and the limited evidence of the use of PDGFR inhibitors and mTOR inhibitors in chordoma." (PMID 36414866, 2023). "In this study, we describe a skull base chordoma harbouring PTEN deletion with consequent loss of PTEN expression and activation of the mTOR pathway." (PMID 36983607, 2023). "This pathway is targeted by mTOR inhibitors and the availability of in vitro models of chordoma cells will aid in further investigating this issue." (PMID 36983607, 2023). "Downstream of PI3K, clinical trials involving mTOR inhibitor combinations have demonstrated modest clinical benefit in chordoma patients, particularly in tumors with mTOR effector activation." (PMID 36387127, 2022). "We also evaluated genes that have been associated with chordoma tumor development, including several members of the SWI/SNF complex, PI3K/AKT/mTOR and Sonic Hedgehog pathways." (PMID 34070849, 2021).
chordoma (continued). "Phosphorylated p70S6kinase expression (p-p70S6K), which lies downstream of TSC2 activation, was also identified; together, these data support the use of mTOR inhibitors to treat chordoma." (PMID 32733369, 2020). "This work paves the way for future in vivo evaluation of CDK / mTOR inhibitor combinations in animal models of chordoma and then in the clinic." (PMID 32737414, 2020). "Few clinical trials investigating PI3K/AKT/mTOR inhibition in chordomas exist to date; current trials implement mTOR inhibitors secondary to other small-molecule inhibitors." (PMID 32733369, 2020). "Several studies have shown the importance of the mTOR signaling pathway in chordoma and suggest it as a promising avenue for targeted therapy." (PMID 32737414, 2020). "Phosphorylated mTOR, the core component of mTORC1 and mTORC2 downstream of activated RTKs, was found in a number of chordoma cases." (PMID 31221659, 2019). "Monotherapy with the mTOR inhibitors rapamycin and everolimus were ineffective in chordoma patients." (PMID 30775316, 2019). "Evidence of activation of thePI3K/AKT/TSC1/TSC2/mTOR signaling pathway was detected in chordoma cells." (PMID 28105324, 2016). "mTOR inhibition merely resulted in reduction in the size of the chordoma cells and had little effect on proliferation and invasion (Data not shown)." (PMID 26247786, 2015). "As proof-of-principle, the authors demonstrate a partial response to the mTOR inhibitor rapamycin, which has shown some success in clinical trials for the treatment of chordoma." (PMID 24311731, 2014). "Of note, p70S6K was activated in five and mTOR in three of our ten chordoma cases analyzed by kinase antibody arrays." (PMID 22613809, 2011). "Generally, the consistent activation of AKT, the frequent activation of p70S6K and of mTOR, together with frequent loss of the TSC1 and PTEN genes, all suggest an important role for the PI3K/AKT pathway in chordoma." (PMID 22613809, 2011). "Inhibitors to mTOR are available and therefore the possibility exists of directed therapy for chordomas." (PMID 19401700, 2009). "On the basis of this study of 50 chordomas, we consider that there is evidence that 65% of the tumours are potentially responsive to mTOR antagonists." (PMID 19401700, 2009). "This figure is generated by the finding that 27% (n=13) of the chordomas exhibit phosphorylated mTOR and a further 18 cases express p-p70S6K although they are negative for p-mTOR." (PMID 19401700, 2009). "Of the 13 (27%) immunoreactive chordomas for p-mTOR, 12 were immunoreactive for total mTOR protein and showed two copies of the mTOR by FISH, where data were available, and all showed phosphorylation of 4E-BP1 and expressed eIF-4E." (PMID 19401700, 2009). "Nevertheless, our findings provide an evidence base for treating selected chordomas with mTOR, AKT inhibitors and antisense molecules to the attractive cancer target, eIF-4E." (PMID 19401700, 2009). "This study focuses on determining if there is evidence for the activation of PI3K/AKT/TSC1/TSC2/mTOR signalling in chordomas in view of existing therapeutic inhibitors." (PMID 19401700, 2009). "As mTOR is found in a region reported to be frequently lost in chordomas and other neoplasms, the tumours were analysed for allelic loss by FISH." (PMID 19401700, 2009). "This emanates from the fact that a partial or complete Phosphatase and Tensin Homolog (PTEN) deficiency generates hyperactivation of the Akt/mTOR pathway, therefore PTEN is a negative regulator of this pathway, and its absence contributes to chordoma development." (PMID 38022609, 2023). "Overall, these observations suggest that treatment with mTOR inhibitors may provide clinical benefits to chordoma patients." (PMID 36983607, 2023). "CH3 cells were sensitive to Rapamycin treatment suggesting that mTOR inhibitors may represent a valuable option for patients suffering from PTEN-deleted chordomas." (PMID 36983607, 2023).